MTOR (mechanistic target of rapamycin kinase)
Diseases named in the same sentence as MTOR in open-access papers (continued):
Sharing a sentence is not in itself a finding about the gene and the disease.
cardiac hypertrophy (continued). "Studies using pressure overload or spontaneously hypertension model, reported that the activation of mTOR signaling is essential for cardiac hypertrophy." (PMID 33377640, 2020). "PTEN is a negative regulator of the PI3K/AKT/mTOR pathways, which are involved in the development of cardiac hypertrophy and dysfunction." (PMID 32595507, 2020). "Our findings revealed that both ALS and RAP played similar roles in Ang II-induced cardiac hypertrophy by neutralizing p-mTOR expression." (PMID 31994601, 2020). "Ddit4l is an autophagy mediator in the heart through mTOR pathways and the balance regulates both physiologic and pathological cardiac hypertrophy." (PMID 33042024, 2020). "Inhibition of mTOR by pretreatment with rapamycin reduces markers of cardiac hypertrophy in this mouse model of ascending aortic constriction, including limiting increases in heart weight and myocyte size." (PMID 32164190, 2020). "On the other hand, it was shown that irisin, a newly discovered myokine, can protect against pressure overload-induced cardiac hypertrophy by inducing autophagy via mTOR-independent activation of the AMPK-ULK1 signaling, both in vivo and in vitro." (PMID 32509147, 2020). "First, mTOR signaling, as the direct regulator of autophagy, has been implicated in ISO- or Ang II-induced pathological cardiac hypertrophy." (PMID 31994601, 2020). "Taken together these data establish a critical connection between SIRT6, mTOR signalling, protein synthesis and cardiac hypertrophy." (PMID 31372634, 2019). "Elevated mTOR activity was detected in cardiac hypertrophy and ischemia/reperfusion-induced heart injury." (PMID 31492659, 2019). "Downregulation of Skp2 activates an mTOR signaling pathway, leading to the suppression of autophagy and an increase in cardiac hypertrophy." (PMID 31547607, 2019). "The heart weight to tibia length ratio was significantly reduced in Torin1 administered mSIRT6-KO mice, indicating that inhibition of mTOR signalling reduced the cardiac hypertrophy." (PMID 31372634, 2019). "Mobilization of this pathway is required for mTOR activation and the development of cardiac hypertrophy." (PMID 30050148, 2018). "Cardiomyocyte-specific miR-199a overexpression inhibited autophagy and induced cardiac hypertrophy via targeting glycogen synthase kinase 3β (GSK3β) involving mTOR signaling." (PMID 30305865, 2018). "Class I HDACs play a “pro-hypertrophic” role in heart and inhibition of this HDAC class attenuates cardiac hypertrophy through tuberous sclerosis complex 2-dependent mTOR repression." (PMID 30081552, 2018). "Mechanistically, the protective effects of AA were mediated by the activation of AMPKα that participates in the pathogenesis of cardiac hypertrophy and inhibition of the mammalian target of rapamycin (mTOR) pathway and ERK." (PMID 30233358, 2018). "At the same time the phosphorylation of p70S6k increased suggesting a stimulation of the mTOR pathway (which promotes cardiac hypertrophy)." (PMID 30134787, 2018). "Conversely, silencing miR-221 in H9C2 cells and cardiomyocytes decreased the levels of phospho-mTOR, phospho-S6K, and phospho-S6, thereby establishing a link between miR-221 and mTOR signaling in the induction of cardiac hypertrophy." (PMID 30305865, 2018). "Simonson found that DDiT4L promotes autophagy and inhibits pathological cardiac hypertrophy in response to stress by inhibiting mTOR-signaling pathways." (PMID 29391491, 2018). "Overexpression of miR-99a suppressed mTOR and attenuated cardiac hypertrophy and cell death in TAC mouse model." (PMID 30305865, 2018). "In contrast, MIAT knockdown or miR-93 overexpression led to a significant inhibition on the protein levels of PI3K, p-AKT, and p-mTOR and blunted Ang II-mediated cardiac hypertrophy." (PMID 30305865, 2018). "High fat diet (HFD) consumption for a prolonged time induces cardiac hypertrophy, and mTOR being a nutrition sensor plays an active role in mediating this effect in the heart." (PMID 30305865, 2018).
cardiac hypertrophy (continued). "The rapamycin-induced autophagy (rapamycin as an inhibitor of mTOR signaling) extended longevity and promoted cardiac performance such as improvement of ejection fraction and reduction in ventricular hypertrophy in aged mice." (PMID 29984246, 2018). "Given the role of mTOR in regulating protein synthesis through S6K and cell cycle control, it is well established that mTOR play a key role in cardiac hypertrophy." (PMID 30305865, 2018). "Studies have demonstrated that atorvastatin plays a positive role in myocardial hypertrophy by augmenting autophagy through the Akt/mTOR pathway." (PMID 29773990, 2018). "It is increasingly apparent that mTOR and miR have a critical role in the development of cardiac hypertrophy and it is becoming important to understand the mechanism by which these two major regulators communicate with each other." (PMID 30305865, 2018). "It is now recognized that p27-mediated inhibition of cyclin-dependent kinase 2 represses mTOR in cardiomyocytes, that p27 can function as an anti-hypertrophic factor, and that p27 is down-regulated during heart failure and cardiac hypertrophy." (PMID 29290979, 2017). "mTOR, being a major growth regulator, plays an integral role in the induction of cardiac hypertrophy in response to pressure overload and MI." (PMID 28373901, 2017). "The cardiomyocyte-specific deletion of mTOR results in severe dilated cardiomyopathy, whereas the pharmacological inhibition of mTOR reverses cardiac hypertrophy." (PMID 28713489, 2017). "The mammalian target of rapamycin (mTOR) is an evolutionary conserved kinase that can modulate cardiac hypertrophy, and increased mTORC1 signaling is an adaptive response to cardiac stress in rat models." (PMID 29073955, 2017). "One of the major signaling pathways regulating cardiac hypertrophy is the pro-hypertrophic mTOR/P70/S6K signaling pathway." (PMID 26914935, 2016). "Taken together, these results indicated that miR-99a inhibits cardiac hypertrophy via an mTOR/P70/S6K Signaling Pathway." (PMID 26914935, 2016). "It is recently reported that mTOR is involved in high-fat diet-Induced cardiac hypertrophy in mice, and AKT/mTOR mediates programmed necrosis in neurons." (PMID 27057269, 2016). "Several intracellular signals elicited by PA are responsible to cardiac hypertrophy, including ER stress and mTOR pathway." (PMID 27057269, 2016). "In turn, increased mTOR activity promotes cardiac hypertrophy, suppresses cardioprotective autophagy, and impairs bioenergetic regulation." (PMID 27528871, 2016). "In a rat model of myocardial hypertrophy (after ligation of arteries), the activity of p70s6k (mTOR’s downstream signaling molecules) increased significantly." (PMID 27321050, 2016). "Here the current evidence suggests that necroptosis is involved in the PA-induced cardiac hypertrophy via activation of AKT/mTOR pathway." (PMID 27057269, 2016). "Some cellular/molecular pathways, including the mitochondrial pathway, phosphoinositide 3-kinase (PI3K), AKT, and mammalian target of rapamycin (mTOR), are involved in the progression of cardiac hypertrophy." (PMID 27213000, 2016). "The AKT/mTOR signaling pathway has emerged as an important regulator in the pathogenesis of myocardial hypertrophy." (PMID 27057269, 2016). "Then we pay attention to AKT/mTOR pathway, which is activated in both physiological and pathological cardiac hypertrophy." (PMID 27057269, 2016). "mTOR signaling has also been reported to enhance cardiac hypertrophy and to be deregulated often in cardiac diseases." (PMID 25826393, 2015). "The mTOR pathway is a critical regulator of cell growth and its activity is known to be altered during cardiac hypertrophy and heart failure." (PMID 25991723, 2015). "Inhibition of mTOR activity by a specific inhibitor, rapamycin, has been shown to attenuate the development of cardiac hypertrophy." (PMID 25826393, 2015).
cardiac hypertrophy (continued). "Cardiac hypertrophy following renal failure can lead to heart failure and we have seen that curcumin abolishes the cardiac hypertrophy in CKD animals by disrupting ERK/mTOR pathway." (PMID 25474287, 2014). "Manipulating the amount of circulating palmitic, palmitoleic, and myristic acids induces cardiac hypertrophy through mTOR signaling." (PMID 24795563, 2014). "This study demonstrates that TR3 positively regulates cardiac hypertrophy by influencing the effect of AngII on the mTOR pathway." (PMID 23197407, 2013). "The mammalian target of rapamycin, mTOR, is widely understood to have an important role in cardiac hypertrophy because of its capacity to regulate cell growth." (PMID 23197407, 2013). "In this study, we provide the first evidence that the orphan nuclear receptor TR3 positively regulates mTOR signalling, and this regulation is amplified in mouse and rat models of AngII-induced cardiac hypertrophy." (PMID 23197407, 2013). "Resistin has recently been shown in rat ventricular myocytes to inhibit AMPK activity, activate TCS2 of the mTOR pathway, and increase cell size leading to cardiac hypertrophy." (PMID 22545721, 2012). "Recently, inhibition of the mTOR pathway by rapamycin was demonstrated to alleviate load-induced cardiac hypertrophy in mice, making it a potential therapeutic target." (PMID 20937113, 2010). "In any case, recent data suggest that, in response to certain hypertrophic stimuli, signaling via mTOR is required for activation of protein synthesis and cardiac hypertrophy." (PMID 17319968, 2007). "Given our observation that MKP-5 deficiency enhances MAPK activity in cardiac muscle from exercised mice, it is plausible that MKP-5-mediated regulation of the MAPK signaling pathway contributes to the activation of the Akt/mTOR signaling pathway, thereby promoting physiological cardiac hypertrophy." (PMID 40136658, 2025). "Therefore, deficiency of PGAM2 results in the downregulation of the HSP90 and its downstream mTOR and client protein IKKα signaling pathway, both of which play crucial roles in the progression of cardiac hypertrophy." (PMID 39897023, 2025). "Furthermore, inhibiting the mTOR signaling pathway can mitigate myocardial hypertrophy induced by pressure overload, suggesting a protective role." (PMID 40355839, 2025). "There have been advances in RALB in cardiovascular disease; for example, RALB is required for autophagy in mTOR-dependent cardiomyocytes, and RALB-associated RalGDS-mediated autophagy induction and exocyst function is critical for load-induced cardiac hypertrophy." (PMID 41398523, 2025). "Another advantage conferred by βOHB is the activation of AMP-activated protein kinase (AMPK), which reestablishes energy homeostasis by blocking the mammalian target of the rapamycin (mTOR) signaling pathway, a recognized promoter of heart hypertrophy and fibrosis." (PMID 41157142, 2025). "Hypertrophic and anabolic signals activated by AAS (e.g., via the Akt/mammalian target of rapamycin (mTOR) pathway) may inhibit autophagy in cardiomyocytes, similarly to other models of cardiac hypertrophy unrelated to AAS." (PMID 41303522, 2025). "Persistent HBP activation has also been shown to induce pathological cardiac hypertrophy through sustained elevated levels of proteins such as the mechanistic or mammalian target of rapamycin (mTOR), a crucial kinase involved in regulation of cell growth and metabolism signaling." (PMID 41382274, 2025). "Furthermore, evidence has been reported that autophagy attenuates phenylephrine‐induced cardiac hypertrophy by inhibiting protein kinase B (Akt)/mammalian target of rapamycin (mTOR) signalling." (PMID 40785055, 2025). "Additionally, the transcription factor EC (TFEC), a basic helix-loop-helix transcription factor, contributes to cardiac hypertrophy by inhibiting AMPK-activated signaling pathways within the mTOR axis." (PMID 40002810, 2025).
cardiac hypertrophy (continued). "Cardiac hypertrophy is an adaptive compensatory mechanism that helps maintain cardiac output in response to harmful stimuli, which can be initiated through two pathways: mTOR and MAPK (ERK), both of which are downstream effectors of AKT." (PMID 39715792, 2025). "Similarly, the deregulation of nutrient and growth signalling pathways and the mammalian target of rapamycin (mTOR) pathway is also found to play an important role in cardiac hypertrophy and aging." (PMID 38612393, 2024). "Furthermore, mTOR is reported to be central to the induction of cardiac hypertrophy after stress, and its inhibition has been reported to improve cardiac function during DCM." (PMID 39239455, 2024). "Taken together, these results suggest that the mechanisms by which DGKζ alleviates pathological cardiac hypertrophy may involve the regulation of Beclin1-mediated autophagy through the mTOR/TFEB signaling pathway." (PMID 38250603, 2024). "The regulation of Beclin1-dependent autophagy by DGKζ may play a role in its impact on cardiac hypertrophy through the modulation of the mTOR/TFEB signaling pathway." (PMID 38250603, 2024). "The inhibition of mTOR with rapamycin alleviates the degree of cardiac hypertrophy in animal model." (PMID 38481817, 2024). "We investigated whether GQ262 inhibits cardiac hypertrophy by suppressing the Akt/mTOR signaling pathway." (PMID 39408627, 2024). "The mTOR signaling pathway is involved in cardiac hypertrophy." (PMID 39355349, 2024). "Subsequently, we investigated whether GQ262 attenuates myocardial hypertrophy through the suppression of the Akt/mTOR signaling pathway." (PMID 39408627, 2024). "Given the role of the PTEN/AKT/mTOR pathway in cardiac hypertrophy and fibrosis, IGFBP2’s modulatory effect on PTEN may influence AF development." (PMID 37435047, 2023). "Apelin-13 reduces PE-induced cardiac hypertrophy by activating the PI3K/AKT/mTOR signaling pathway." (PMID 36742144, 2023). "They concluded that mTOR inhibition could reverse necroptosis triggered by increased saturated fatty acid to treat myocardial hypertrophy." (PMID 38164133, 2023). "Also, it has been clarified that the overexpression of 5-hydroxytryptamine receptor 2A was involved in cardiac hypertrophy through the AKT/mTOR signaling pathway." (PMID 36742144, 2023). "Similarly, the Akt/mTOR pathway was detected in our research when autophagy was involved in the mechanism of G1 protecting cardiac hypertrophy." (PMID 36674423, 2023). "However, the inhibitory effects of Trim44 KO on pathological cardiac hypertrophy induced by ISO treatment were exerted by suppressing the AKT/mTOR/GSK3β/P70S6K signaling pathway." (PMID 35855640, 2023). "It has been confirmed that the Krüppel-like factor could inhibit isoproterenol-induced cardiac hypertrophy through AKT/mTOR signaling pathway." (PMID 36742144, 2023). "However, sustained mal-regulated activation of mTOR during heart failure promotes ventricular hypertrophy as well as detrimental cardiac remodeling; however, partial inhibition of mTOR prevents ventricular fibrosis in hypertrophic cardiomyopathy models." (PMID 37691190, 2023). "Previous studies by Chen L. had shown that pinoresinol diglucoside could inhibit isoproterenol-induced cardiac hypertrophy through AKT/mTOR signaling pathway." (PMID 36742144, 2023). "The activation of AMPK inhibits translation and transcription in the process of protein synthesis, directly phosphorylates eucaryotic elongation factor 2 kinase (eEF2K) to inhibit protein prolongation, inhibits mTOR signaling pathway, so as to inhibit the process of cardiac hypertrophy." (PMID 37063954, 2023). "Polyphenol modulation of mTOR via the PI3K/AKT pathway could be beneficial for the prevention of cardiac hypertrophy and preserving β-cell function." (PMID 36670985, 2023). "This also suggested that Apelin-13 could improve cardiac hypertrophy by activating PI3K/AKT/mTOR signal pathway." (PMID 36742144, 2023).
cardiac hypertrophy (continued). "In addition to the effective treatment of CVD, mTOR inhibitors have proven to be effective therapies for hypertensive heart diseases, such as hypertension, heart failure and cardiac hypertrophy." (PMID 37108307, 2023). "Isoproterenol-induced cardiac hypertrophy could be alleviated by curcumin by enhancing autophagy via AMPK/mTOR." (PMID 35880107, 2022). "Moreover, rapamycin specifically identifies and blocks testosterone-induced OVX SHR cardiac hypertrophy through mTOR signaling pathway." (PMID 34874016, 2022). "TRIM 27 therefore contributes to cardiac hypertrophy by activating the PTEN/Akt/mTOR axis." (PMID 36200036, 2022). "Therefore, short-term treatment with rapamycin, an mTOR inhibitor, is a promising treatment strategy for acute myocardial infarction and cardiac hypertrophy." (PMID 35557532, 2022). "In conclusion, this study demonstrates that the regulation of mTOR/S6K1/4E-BP1 signaling pathway may be one of the important mechanisms for the occurrence of myocardial hypertrophy in testosterone-induced OVX SHR." (PMID 34874016, 2022). "The effects seen in cardiac hypertrophy models showcase the ability of TH to genomically signal via TRα1 and TRβ1 and induce Akt/mTOR survival signaling, which confers cytoprotection and leads to increased synthesis of normal contractile proteins and hypertrophic gene upregulation." (PMID 36133808, 2022). "Along these same lines, AKT and mTOR represent critical players in angiogenesis throughout physiological cardiac hypertrophy, proposing that the dislocation of these molecules may induce pathological hypertrophy." (PMID 35628576, 2022). "Aortic constriction-induced myocardial hypertrophy is accompanied by an increase in mTOR activity." (PMID 34874016, 2022). "Furthermore, we find that MKK3/p38γ/δ hyperactivation in MKK6 KO mice promotes cardiac hypertrophy through mTOR activation, which progresses to a pathological cardiac hypertrophy phenotype with age and development of cardiac dysfunction." (PMID 35971771, 2022). "WT mice that consumed a BCAA-rich meal at the end of the active phase (dark phase) revealed cardiac remodeling and influence on cardiometabolic parameters, with increased responsiveness of BCAA-induced mechanistic target of rapamycin (mTOR), the signaling pathway involved in cardiac hypertrophy." (PMID 36557311, 2022). "It has also been discovered to improve the mitochondrial function of cardiomyocytes by regulating mitochondrial biogenesis-related proteins and inhibiting apoptosis while attenuating cardiac hypertrophy by autophagy regulation through the PI K/AKT/mTOR pathway." (PMID 36704479, 2022). "In addition, melatonin prevented myocyte apoptosis and autophagy dysfunction by Atg5‐ and Akt/mTOR‐dependent pathways in pressure overload‐induced cardiac hypertrophy." (PMID 35170783, 2022). "Even though mTOR inhibition suppresses myocardial hypertrophy due to mechanical loads in animal models, it has been revealed that overexpression of mTOR lowers cardiac dysfunction as a reaction to hypertrophy caused by pressure overload and lowers the inflammatory response." (PMID 35163076, 2022). "The AMPKα/mTOR pathway is an important regulator of pathological cardiac hypertrophy." (PMID 35592411, 2022). "Mechanistically, Akt/mTOR/p70s6k may be involved in the protective role of Trim27 against cardiac hypertrophy both in vivo and in vitro." (PMID 35311628, 2022). "Our findings suggest that the mTOR-independent translation control might contribute even more to the accelerated protein synthesis during cardiac hypertrophy." (PMID 34977198, 2021). "In addition, mTOR functions as an important regulator to inhibit mTORC1 during the progression of cardiac hypertrophy." (PMID 34674743, 2021). "Discovering new targets for regulating AMPK/mTOR signaling pathway might efficiently inhibit the development and progress of cardiac hypertrophy and heart failure." (PMID 34867324, 2021).